IL2 (interleukin 2)
Diseases named in the same sentence as IL2 in open-access papers (continued):
Sharing a sentence is not in itself a finding about the gene and the disease.
tumor (continued). "The reduction in IL-2 was noticeably less of an effect than the heightened killing of the tumour cells by the Jurkat cells." (PMID 37973660, 2023). "In agreement with the less exhaustion and apoptosis, tumor infiltrating TCR-JUN T cells produced nearly 2-folds of IL-2 and IFNγ." (PMID 37215108, 2023). "An in vitro analysis of the tumor sections revealed homogenous staining by IL2-7NP2-TNFmut, confirming the cellular expression of human FAP similar to the staining observed with 7NP2 in an IgG1 format." (PMID 37092450, 2023). "Compared to IL-2, IL-2superkines induced superior expansion of cytotoxic T cells, more prolonged and more intense NK cell activation, and improved anti-tumour responses in different syngeneic mouse models." (PMID 37388731, 2023). "TILs are naturally occurring heterogeneous groups of lymphocytes infiltrating solid tumors that can be isolated from the tumor site and expanded ex vivo by adding the T cell growth factor interleukin-2 (IL-2)." (PMID 38020120, 2023). "Both IL-2 and IL-10 were found to increase the anti-tumor cytotoxic activity of CD8+ T cells in vitro and a potential synergistic effect for the two cytokines." (PMID 37520880, 2023). "The apoptotic properties of spheroids created with a 3D tumor model and applied 5FU/IL2/CD nanoplexes were determined using the TUNEL kit." (PMID 36839637, 2023). "Theragnostic biomarkers like IDO1, s-CTLA-4, IFN-γ, TNF-α and IL-2 have been studied in various tumors, and seems to hold significant potential in mapping the tumor microenvironment and predicting response to ICPIs." (PMID 36879122, 2023). "The interaction occurs by binding D1 and D2 domains of LAG-3 with FGL-1, leading to reduced IL-2 levels in the tumor microenvironment." (PMID 36680187, 2023). "In another study using the B16-F10 aggressive melanoma murine model, treated with anti-PD1 Ab, propranolol, and IL-2 interventions, the most statistically significant delay in tumor growth was in animals administered the anti-PD1 Ab/propranolol combination." (PMID 38299150, 2023). "The influx of functional T cells, i.e., T cells that produce anti-tumor cytokines, including IL-2, IFN-γ, and TNF-α, in the TME of the Lm-LLO-ISG15-vaccinated group was higher than that of the Control Lm-treated group." (PMID 36831577, 2023). "IL-2 exerts its anticancer activity by binding to IL-2 receptors and promoting the proliferation of tumor-reactive T cells, which can specifically target and attack tumors in the body." (PMID 37256141, 2023). "Consistently, PC treatment up-regulated the level of γc in tumor-infiltrating lymphocytes, inhibited tumor growth, and sensitized the anti-tumor effects of IL-2 as well as its combination with PD-1 blocking antibody." (PMID 37932447, 2023). "Many studies have confirmed that IL-2 has antiviral, anti-tumor and immune-enhancing effects and can also play a pro-inflammatory role under certain conditions." (PMID 36691058, 2023). "Liver and electrolyte levels were normal, but CRP was elevated in response to tumor progression, IL-2 administration, or infection." (PMID 36765608, 2023). "The Th1 phenotype can secrete IFN-γ, IL-2, and other factors to fight tumors, but IL-4 and IL-5 secreted by the Th2 phenotype have tumor-promoting effects." (PMID 36844875, 2023). "Recent studies have shown that CAR-T cells armed with engineered interleukin-2 (IL-2) and interleukin-33 (IL-33) promote tumor control as a single-agent therapy." (PMID 38516299, 2023). "Cytokines such as IL-15 or IL-2, which stimulate an anti-tumor immune response, have been shown to have a particularly high potential for use in immunotherapy against various tumors." (PMID 38002466, 2023). "This type of ACT is based on the isolation of TILs from patient tumor biopsy followed by in vitro stimulation with Interleukin 2 (IL-2)." (PMID 37443821, 2023).
tumor (continued). "These tumor suppressor cells, such as cytotoxic T lymphocytes, also upregulate the release of pro-inflammatory cytokines, namely, IL-2, IL-6, IL-12, INF-γ, and TNF-α." (PMID 37238966, 2023). "Their function and expression in the tumor microenvironment make them attractive targets for immunotherapy, leading to the development of IL-2/IL-2R-targeted therapeutic strategies." (PMID 37516849, 2023). "IL-2/IL-2R signaling plays a pivotal role in modulating immune cells, and its dysregulation can contribute to tumor evasion." (PMID 37516849, 2023). "Namely, direct comparison to CAR constructs with proven clinical efficacy if available, use of targets expressing physiological levels of antigen, assessment of IL-2 release and prolonged tumor control on repeated stimulation." (PMID 37399355, 2023). "Another engineering method is the incorporation of cytokine armoring genes, which leads to the production of cytokines required for T cell growth, including IL-15, IL-2, IL-7, IL-12, and IL-21, hence strengthening tumor-killing abilities." (PMID 37064017, 2023). "Apart from HOBIT, the IL2-dependent induction of the HOBIT homolog BLIMP1 was shown to be critical for induction of granzymes in tumor-specific CD4 T cells." (PMID 37654482, 2023). "On the other hand, the level of IL-2 was enhanced by the treatment with UA compared with untreated tumor-bearing control animals." (PMID 36768978, 2023). "The combined application of PD-1v, IL-2/15, IL-12, and GM-CSF recombinant plasmids significantly inhibited tumor growth in mice, and the tumor growth rate was significantly lower than that in the blank control group and GFP plasmid control group (p < 0.05)." (PMID 37199371, 2023). "Whereas tumor-inhibiting cytokines including IFN-α, IL-2, and IL-12, inhibit tumor growth and angiogenesis, and expand the functional T-cells and Natural killer cells." (PMID 37298889, 2023). "A single intratumoral administration of IL‐2‐laden FPC2‐IG (FPC2‐IG‐IL‐2) augmented the therapeutic efficacy of antitumor T cells in preclinical mouse tumor models." (PMID 36684086, 2023). "Additional expression of PD-1-CD28 shielded TRuC T cells from PD-L1-induced immunosuppression and increased IFN-γ and IL-2 release in the presence of PD-L1 + tumor cells." (PMID 36409438, 2023). "This phenomenon increases the immunogenicity of the tumor microenvironment once DAMPs induce the maturation of DCs, and pro-inflammatory cytokines, such as IL-2, IL-6, IL-12, INF-γ and TNF-α, were also reported to increase." (PMID 37238966, 2023). "Interactions mediated by IL-2-based antibody–cytokine fusion proteins induce polarization, increase cell adhesion, and activate immune synapse formation between tumor and IL-2R+ NK cells, facilitating their cytotoxic functions." (PMID 36839658, 2023). "Both primary IL-2 stimulated NK cells and sNK cells had significantly lower cell index compared to tumor alone and tumor with primary untreated NK cells at 24 and 48 hours." (PMID 37954598, 2023). "It has been shown that ex vivo-expanded NK cells exhibit higher cytokine secretion profiles and have stronger cytotoxicity against tumor cells, and the maintenance of this activation depends on the presence of IL-15 or IL-2." (PMID 38003255, 2023). "Modified S. typhimurium that expressed interleukin-2 were able to induce tumor regression or slow tumor growth in melanomas and osteosarcomas and prevent the formation of metastases." (PMID 37629016, 2023). "In mice bearing the H22 tumor, chiisanoside (120 mg/kg and 240 mg/kg) effectively suppresses tumor growth while upregulating the expression of cytokines such as IL-2, TNF-α, and IFN-γ." (PMID 37764339, 2023). "With low levels of T cells present in CSF, IT interleukin-2 (IL-2) administration has been used in order to generate an immune response against immunogenic tumour cells in CSF." (PMID 37511202, 2023).
tumor (continued). "Among the effector functions of CD8+ T cells, it is important to mention the release of IL-2 (recruiting NK cells) and interferon-gamma (disrupting tumor proliferation and angiogenesis)." (PMID 36768649, 2023). "Upregulation of CD276 promoted the immune escape of tumor cells and reduced secretion of interleukin-2 (IL-2), tumor necrosis factor-alpha (TNF-α) and other cytokines." (PMID 36713082, 2023). "A recent study has shown that high level of IL-2 induces the conversion of tryptophan to 5-hydroxytryptophan (5-HTP), and 5-HTP activates AhR, thereby causing T cells dysfunctional in the tumor microenvironment." (PMID 36966295, 2023). "Systemic blockade of TGF-β with anti-TGF-β antibodies in combination with DNA vaccination or IL-2 treatment enhances tumor-infiltrating and tumor-reactive CD8+ T cells." (PMID 36750317, 2023). "The proinflammatory cytokines Il‐2, Tnf‐α, and Ifn‐γ were found significantly enhanced in tumor tissues from mice with G4 vaccine treatment." (PMID 37222047, 2023). "Rantes (CCL5), which can induce anti-tumor immunity and cooperate with Th1 cytokines, such as IL-2 and IFN-γ, was found to be decreased after EV treatment on CD8 + T-cells." (PMID 37884996, 2023). "Naïve Th cells that are activated develop into Th1 cells that hamper tumor progression through the production of interleukin (IL)-2 and interferon-gamma (IFN-γ), which increases the phagocytosis of tumor cells and the antitumor immune response." (PMID 36836712, 2023). "Interaction between CTLA-4 on T cells and CD80 on tumor cells leads to protein kinase B (Akt) pathway inhibition and IL-2 function in T cells." (PMID 36816749, 2023). "TILs LN-145-S1 are autologous tumour-infiltrating lymphocytes (TILs) isolated from an autologous tumour sample and expanded ex vivo in the presence of interleukin-2 (IL-2)." (PMID 37568740, 2023). "The effectiveness of high-dose IL-2 therapy, immune checkpoint inhibitors, and TILs in treating cancer relies on the presence of pre-existing tumor-reactive T cells in patients." (PMID 37256141, 2023). "TIL-based ACT relies on (i) non-myeloablative lymphoid exhaustion, (ii) tumor-specific T cells isolated from tumor tissues, expanded in vitro, and injected into the host, and (iii) IL-2 administration after TIL infusion." (PMID 36923404, 2023). "Our results to date have demonstrated that CU06-1004 can reduce IL-2-induced vascular leakage in a tumor-bearing mouse model." (PMID 37711172, 2023). "The authors argue that the combination of PD-L1 knockdown siRNA and immunostimulatory pDNA/IL-2 delivered using LNPs reduces the drug resistance rate and leads to enhanced anti-tumor activity while also providing tumor-selective therapeutic properties." (PMID 36865093, 2023). "We found that changes in tumor size correlated with the number of cytotoxic CD8+ T cells in both the IL-2-alone and CU06-1004-combined treatment groups." (PMID 37711172, 2023). "GCT02 and 2173 CAR T cells secreted IFN‐γ and IL‐2 equivalently and specifically in response to EGFRvIII‐expressing tumor cell lines." (PMID 36890859, 2023). "Jun Ishihara and colleagues reported a fusion protein of IL-2 and vWF A3-CBD, which reduced splenomegaly and pulmonary edema induced by IL-2-related vascular leakage and improved its anti-tumor efficacy in C57BL/6 B16F10 allograft mouse model." (PMID 37692860, 2023). "In the late 1990s, Rosenberg and colleagues reported the durability of anti-tumor responses in cancer patients treated with IL-2." (PMID 37174716, 2023). "Conversely, IL-2 is a critical cytokine that promotes T cell survival and activity, improves infection and tumor immune responses, and counteracts T cell depletion." (PMID 37250453, 2023). "Among interleukin-mediated signaling pathways, IL6 and IL2 are established inflammatory factors involved in tumor immunity regulation by facilitating lymphocyte growth and function." (PMID 36759763, 2023).
tumor (continued). "They observed that IL-2 treated PTC cells can limit tumor progression by increasing activation of CD8 + T cells and downregulation of immune checkpoint inhibitor PD-1." (PMID 37563607, 2023). "The outcomes were indicative of the successful functionality of derived MSCs from the amniotic fluid as a delivery carrier of IL-2 to the desired tumor sites." (PMID 36742134, 2023). "The treatment was well-tolerated, and tumors of treated mice showed a modest reduction in tumor growth rate, as well as significantly elevated levels of IL-2 in the tumor." (PMID 37532747, 2023). "Studies have shown that IL2 can inhibit tumor cell proliferation by influencing JAK-STAT signaling pathway through autocrine mode." (PMID 38259290, 2023). "We note that bispecific constructs currently called immunocytokines link a cytokine to a targeting antibody with the intent to deliver cytokines such as IL-2 to T cells in the tumor microenvironment." (PMID 36138170, 2023). "Second, mouse tumor specimens were assessed for IL-2, IL-10, and CD4 levels by immunohistochemistry." (PMID 37253929, 2023). "While anti-CD137 and IL-2-Fc fusion proteins demonstrate strong anti-tumor effects, they can also trigger a robust systemic immune response, potentially leading to severe immune-related side effects." (PMID 37808190, 2023). "In conclusion, the role of IL-2 and IL-2R within the tumor microenvironment remains a fascinating and vital area of exploration." (PMID 37516849, 2023). "The immune responses of TCR-engineered Jurkat cells or primary T cells were detected using IL-2 or IFN-γ ELISPOT or ELISA assays after co-culturing with target cells loaded with peptides or tumor cells intrinsically expressing KRAS mutants." (PMID 37828002, 2023). "Currently, IFN-α and IL-2 have become the most widely used drugs in tumor immunotherapy strategies, however, several other cytokines are currently under clinical investigation." (PMID 37081982, 2023). "In summary, tumor size reduction by IL-2 drugs is expected to be related to the number of CD8+ T cells in the tumor and the expression of pro-inflammatory cytokines." (PMID 37711172, 2023). "Rosenberg and colleagues demonstrated that giving mice recombinant IL-2 resulted in substantial anticancer action, including the regression of existing lung metastases and subcutaneous tumours." (PMID 37162544, 2023). "IL-2 is capable of promoting T-cell proliferation and activation, which is essential for tumor-killing activity." (PMID 37275909, 2023). "T cells with the exhausted phenotype cannot produce effector factors to successfully target tumor cells, resulting in the decreased secretion of IL-2 and IFN-γ." (PMID 36891319, 2023). "This heterogeneity underscores the need for a personalized approach to IL-2-based immunotherapy, with future strategies potentially requiring tailoring based on individual patient characteristics and tumor profiles." (PMID 37516849, 2023). "Anti-tumor immune reactivity has also been shown to be subject to cytokine (type I and II IFNs, IL-2, IL-7, IL-12, IL-15, IL-18, and IL-21) regulation and augmentation in preclinical and clinical settings." (PMID 36677048, 2023). "Th1 cells produce IFN-γ to induce M1-polarization of macrophages, and produce IL-2 to enhance the function of T cells; M1 macrophages recruit Th1 cells and NK cells for synergistic anti-tumor function." (PMID 37063892, 2023). "Another promising avenue is using IL-2 as an adjuvant in cancer vaccines to bolster the activation and proliferation of tumor-specific T cells." (PMID 37516849, 2023). "Administration of IL-2 in March5+/f:Vav1-Cre mice showed increased efficacy in suppression of tumor growth and improvement of the overall survival comparing to that in March5+/f mice." (PMID 37932447, 2023). "Pleural T cells, activated and expanded in the presence of CD3/CD28 beads plus IL-2 are potent cytotoxic effectors against autologous tumor as measured by LDH release." (PMID 37063842, 2023).
tumor (continued). "We also identified Pitavastatin Calcium as an inhibitor of MARCH5, which combined with PD-1 blockade and IL-2 significantly improves the efficacy of anti-tumor immunotherapy in mice." (PMID 37932447, 2023). "IL-2/IL-2R signaling plays a pivotal role in the activation and proliferation of TILs, immune cells that infiltrate tumors and mediate anti-tumor immune responses." (PMID 37516849, 2023). "Engineered forms of IL-2 have been developed to improve its anti-tumor activity while reducing toxicity." (PMID 37516849, 2023). "A deeper understanding of these mechanisms can pave the way for novel strategies targeting IL-2/IL-2R signaling to enhance neutrophils’ anti-tumor activities or minimize their pro-tumor activities." (PMID 37516849, 2023). "IL-2 can enhance the anti-tumor immune response and reduce tumor growth, as demonstrated in mouse cancer models." (PMID 37516849, 2023). "In the tumor microenvironment, IL-2 and its IL-2R have complex and sometimes opposing roles in tumor progression and immune response." (PMID 37516849, 2023). "High-dose IL-2 has anti-tumour and enhanced immune effects, while low-dose IL-2 has immunosuppressive effects." (PMID 37596509, 2023). "The combination of propranolol and IL-2 also resulted in a significant delay in tumor growth, making it a potential combinatory treatment." (PMID 38299150, 2023). "Cytokines, such as interferon (INF)-alpha and interleukin (IL)-2, also play a crucial role in tumor immunotherapy." (PMID 37081982, 2023). "Pro-inflammatory cytokines such as IL-2, IL-12, and IL-15 can improve antigen priming, increase the number of effector immune cells in the tumor immune microenvironment and enhance cytolytic activity." (PMID 36937769, 2023). "Local administration of an IL-2-expressing vaccinia virus (VV-IL-2) significantly reduced tumor burden, due to the increase in the activity of immune cells including CD4+ and CD8+ T cells and α,β T-cell receptor diversity in a malignant pleural disease model." (PMID 37345057, 2023). "We designed ACC by engineering genetic fusion of a cytokine (such as the IL-2 mimetic Neo2/15) on the C-terminus of the constant heavy chain of a tumor-specific anti-Tyrp1 antibody TA99." (PMID 36911698, 2023). "Together, these results show that NK cells expanded in vitro with CD3, IFN-γ, IL-2, and irradiated PBMCs as feeder cells had greater anti-tumor activity than resting NK cells." (PMID 37169953, 2023). "The review concludes that a deeper understanding of IL-2/IL-2R interactions within the tumor microenvironment is crucial for realizing the full potential of IL-2-based therapies, heralding the promise of improved outcomes for cancer patients." (PMID 37516849, 2023). "Combination therapy with PD-1 blockade and IL-2 substantially improves anti-tumor efficacy comparing to monotherapy." (PMID 37932447, 2023). "Under the section of whole ATC vaccines, a combination of preconditioning with IL-2 prior to subsequent vaccination led to an augmented anti-tumor response in HNSCC patients." (PMID 36992219, 2023). "Initially, and with the assumption that the main function of IL-2 was the activation of effector T cells and NK cells, efforts to exploit IL-2 in immunotherapy were focused on promoting anti-tumour immunity." (PMID 37741949, 2023). "NK cells can be primed by either IL-2 or by contact with a tumour cell that triggers tumour cell lysis." (PMID 37957274, 2023). "This indicated that the released IL‐2 from FPC2‐IG‐IL‐2 can efficiently support the expansion of tumor‐infiltrating, adoptively transferred, tumor‐reactive T cells." (PMID 36684086, 2023). "In the context of immunotherapy, CD8+ T cells play a pivotal role, secreting cytokines such as IFN-γ, TNF-α, and IL-2 to exert cytotoxic effects on tumor cells." (PMID 38299141, 2023). "Through activating CTLA-4, NF-ĸB signaling is blocked and IL-2 production is inhibited, so anti-tumor immune responses by tumor cytotoxic T lymphocytes and NK cells become limited." (PMID 37735675, 2023).